IL13 (interleukin 13)
Diseases named in the same sentence as IL13 in open-access papers (continued):
Sharing a sentence is not in itself a finding about the gene and the disease.
infection (continued). "Resistant animals produce high levels of interleukin 13 (IL-13) and associated T helper type 2 (Th2) cytokines in response to infection, which is essential for parasite expulsion." (PMID 24628794, 2014). "Conversely, a Th2 response is associated with susceptibility to infection which is driven by high IL-4, and IL-13 and reduced intracellular parasite killing due to increased Arginase-1 activity." (PMID 24801628, 2014). "Intriguingly, recent studies have shown that RAG−/− mice deficient in vitamin A expand the numbers of IL-13-producing ILC2 following even low-dose infections of T. muris and that this is reflected by increased GC numbers." (PMID 24942690, 2014). "It was demonstrated that L. major phosphomannomutase (PMM) deficient mutants were able to protect susceptible mice against infection via an increased magnitude of T cell responses and suppression of IL-10 and IL-13 production early during infection." (PMID 23554800, 2013). "Transfer of B cells from MyD88−/− mice into naive mice resulted in impaired control of infection, associated with lower IL-13 production by T cells in the mediastinal lymph node." (PMID 24204255, 2013). "Plasma IL-10 increased significantly in children with previous episodes or current infection, and higher levels of IL-12 and IL-13 were also associated with previous episodes." (PMID 22280502, 2012). "This is consistent with what occurs in intact mice, where infection of infants increased the release of the pro-asthmatic Th2 cytokines IL-5 and IL-13, which was associated with increases in MSC numbers and AHR." (PMID 22870337, 2012). "The immune cells of mice deficient in IL-13 phagocytose more C. muridarum and their lung cells have less infection." (PMID 21573182, 2011). "Conversely CD4+ T cell specific (LckcreIL-4Rα−/lox) IL-4Rα−/− mice are more susceptible than global IL-4Rα−/− mice to infection with L. mexicana, indicating a role for an IL-4/IL-13 responsive non CD4+ T cell population in early susceptibility." (PMID 21245915, 2011). "Significantly, the depletion of IL-13 resulted in decreased susceptibility of LA4 cells to infection." (PMID 21573182, 2011). "Here, we show that IL-13 was produced in the lungs of mice rapidly after Chlamydia muridarum (Cmu) infection and promoted susceptibility to infection." (PMID 21573182, 2011). "IL-13 has been described as a susceptibility factor for infection with both Leishmania major and Crytococcus neoformans." (PMID 21573182, 2011). "Wild-type (WT) mice had increased disease severity, bacterial load and associated inflammation compared to IL-13 deficient (−/−) mice as early as 3 days post infection (p.i.)." (PMID 21573182, 2011). "Our in vitro evidence that IL-13 increases the susceptibility of airway epithelial cells to infection with Cmu also supports this concept." (PMID 21573182, 2011). "We also found that IL-18R deficient mouse lungs have significantly elevated levels of IL-13 at day 12 following infection." (PMID 22039448, 2011). "A multivariate analysis was then performed between IL13 polymorphisms and high infection levels, taking into account age, gender and the village of origin." (PMID 19471606, 2008). "However, as infection progressed, IL-13 levels recovered in T cell-specific SLC7A5-deficient mice, alongside resistance." (PMID 41809569, 2026). "Notably, CpG sites associated with Il4, Il13, Cd200, and Il1rl1 displayed the lowest methylation levels on Day 1 of infection, followed by an increase over time." (PMID 40170749, 2025). "Indeed, in the mouse model, Th2 responses have been correlated with protection against pathology, while IL-13 was associated with both clearance and susceptibility to infection." (PMID 38166152, 2024). "Three cytokines, IL-4, IL-13, and G-CSF were also found to be associated with the immunoglobulin genes, and are known to be involved in the immunoglobulin response cascade during an infection." (PMID 37918965, 2024).
infection (continued). "This therefore increases risk of infection as IL-13 may have a role in both larval and egg protective immunity." (PMID 34281269, 2021). "However, higher GM infection intensities were realized among pupils aged 12–14 years who were homozygous for the T allele with regard to the IL13-1055C/T (i.e. T/T), and for the G allele with regard to the IL13-1258A/G (i.e. G/G) polymorphisms." (PMID 34185775, 2021). "Resistant animals produce high levels of interleukin 13 (IL-13) and associated T helper type 2 (Th2) cytokines in response to infection, which are essential for parasite expulsion via mechanisms such as epithelial cell turnover and mucin production and muscle contraction." (PMID 34078488, 2021). "Infection intensity levels however appeared higher among pupils aged 12–14 years who were homozygous for the T and G alleles with regard to the IL13-1055C/T (i.e. T/T; N = 2) and IL13-1258A/G (i.e. G/G; N = 1) polymorphisms." (PMID 34185775, 2021). "Perhaps IL-13 secreted by innate immune cells in the early stage of infection is mainly associated with pathogenicity, while in the late stage of infection, IL-13 produced by specific T cells, especially those have immune memory, exert protective effect in anti-infection immunity." (PMID 34093528, 2021). "Notably, proinflammatory cytokine genes Il-1α, Il-6, Il-7, and Il-17, as well as anti-inflammatory genes Il-6 and Il-13, were downregulated after an infection caused by the 267/47 strain compared to those after infection with the H37Rv strain." (PMID 34442871, 2021). "We were able to detect significant elevation in IL-13 associated with S. haematobium infection, particularly at the site of damage, supporting the idea that type 2 immune responses occur in the context of human infection." (PMID 34662329, 2021). "In addition, it has been shown that STAT6 (the signal transducer activated by the IL-4/IL-13 pathway) contains the rs324013 polymorphism, which was found in patients exhibiting higher levels of infection." (PMID 34281269, 2021). "Associations with infection were replicated at two SNP (IL13 rs1800925; IL4 rs2243250), and both of these SNP and also the IL10 (−1082/−819/−592) haplotype were also found to be associated with pathology, despite the studies using different phenotypes and in one case different parasite species." (PMID 33659002, 2021). "Moreover, two SNPs in the IL-5 and IL-13 genes, which appeared to be associated with infection susceptibility, had to be considered as likely due to chance, because both associations were no longer significant upon permutation testing." (PMID 34185775, 2021). "Only Tbet-deficient mice show IL-13 expression after RV-A1B-infection." (PMID 33968043, 2021). "Furthermore, IL-4 and IL-13 inhibit the skin production of antimicrobial peptides and, thus, predispose AD skin to colonization and infection of Staphylococcus aureus, which further worsens skin inflammation and barrier defects." (PMID 34829844, 2021). "To confirm that a lack of IL-13 expression could be the cause of diminished worm clearance, we injected rIL-13 into Egfrfl/flxCd4-cre mice at days 6, 7, and 8 post infection." (PMID 29045902, 2017). "Finally, infection of mice with recent clinical isolates of RSV with known human pathogenic potential demonstrated a similar induction of IL-13+ ILC2s at day 4 after infection that required TSLP." (PMID 27156176, 2016). "Additionally, infection of mice with 2 recent clinical isolates of RSV with known human pathogenic potential similarly induced IL-13–producing ILC2s through a TSLP-dependent mechanism." (PMID 27156176, 2016). "Both IL-4 and IL-13 are important in host defense against T. spiralis, likely with different regulatory pathways, where NK cell derived IL-13 may cause some of the pathology associated with infection." (PMID 27267469, 2016).
infection (continued). "However, pentoxifylline diminished secretion of TNF-α, IFN-γ and IL-13, cytokines associated with the outcome of infection by species of the Viannia subgenus." (PMID 26024228, 2015). "Moreover, the number of IL-5- and IL-13-producing CD4 T cells was significantly (p<0.01) reduced in FI-RSV-immunized STAT6-deficient mice at day 7 post-infection." (PMID 25769044, 2015). "In addition to antigen presentation we also demonstrate IL-4Rα-dependent increases in IL-13 production by endogenous B cells to be associated with control of secondary infection." (PMID 24204255, 2013). "Thus, infection of STAT1-deficient mice with RSV strain A2 resulted in elevated IL-13 and IL-17 levels, production of excess mucus and airway inflammation." (PMID 23462708, 2013). "Moreover, similar to IL-4 KO mice, neutralization of IL-13 in female p55/p75 KO mice rendered them susceptible to infection and administration of recombinant IL-13 to male p55/p75 KO animals restored parasite expulsion." (PMID 23053395, 2012). "It is also possible that IL-13 may condition the respiratory epithelium so that it is more susceptible to infection, thus the action of IL-13 is on structural cells as well as non-lymphoid cells that play key roles in host defence pathways." (PMID 21573182, 2011). "Furthermore IL-13 deficiency suppresses the development of clinical signs infection as a result of an enhanced ability to clear the bacteria." (PMID 21573182, 2011). "Indeed IL-13 has been identified as a susceptibility factor for infection of mice by the protozoan parasite Leishmania major by suppressing the expression of IFNγ and IL-12." (PMID 21573182, 2011). "However, mice deficient in IL-13 have reduced clinical symptoms and numbers of C. muridarum in their lungs after infection." (PMID 21573182, 2011). "An association between an IL13 polymorphism, rs1800925, and infection levels has been shown." (PMID 19471606, 2008). "However, the central dogma of Th1 and Th2 cells and their signature cytokines, INF gamma and IL-4/IL-13 related to resistance or susceptibility to infection is changing toward interconnected pathways in which depending on the disease model, the IL-4 and even the IL-13 can mediate Th1 immunity." (PMID 39119291, 2024). "However, once Schistosoma eggs are produced at 5–6 weeks of infection, the host immune status dramatically shifts to a Th2 response, as shown by the increased production of Th2-associated cytokines IL-4, IL-5, IL-10, and IL-13." (PMID 35584107, 2022). "However, IL-13 can play a role in the differentiation of Th2 cells, and it was therefore possible that increased worm burden in IL-13 deficient mice was due to impaired Th2-cell activation after infection." (PMID 34127548, 2021). "Herein, the relative expression fold change values of IL-4 and IL-13 were next to those of IL-23, IL-1β, and IL-22, suggesting that a higher expression of Th2-associated cytokine genes coincided with the increased percentage of Th2 cells after infection with intravenous injection." (PMID 33441700, 2021). "In addition, high IL-13 and IL-5 expression could also be used to detect patients at risk of developing acute exacerbations of infection." (PMID 28680858, 2017). "In addition, we found a higher relative production of Th2 cytokines (IL5, IL13) in response to mitogen stimulation (expressed as cytokine response ratio) rather than the lack of cytokine response to be associated with increased risk for infection." (PMID 29051761, 2017). "Conversely, susceptibility to infection and disease progression in CL is driven predominantly by the induction of a non-protective IL-4 Th-2-type response and the production of Th-2 associated cytokines such as IL-4, IL-10, IL-13 and transforming growth factor (TGF)-β." (PMID 27094260, 2017).
infection (continued). "In BALB/c mice, susceptibility to infection with the intracellular parasite Leishmania major is driven largely by the development of T helper 2 (Th2) responses and the production of interleukin (IL)-4 and IL-13, which share a common receptor subunit, the IL-4 receptor alpha chain (IL-4Rα)." (PMID 24204259, 2013). "Notably, mice deficient in IL-25 (IL-17BR−/−) or IL-33 (T1/ST2) receptors mount poor type 2 responses and are more susceptible to infection with Nippostrongylus brasiliensis, while immunity can be restored to these animals by transfer of ILCs acting in an IL-13-dependent manner [13••]." (PMID 22795966, 2012). "Alternatively, the observed association of IL4 polymorphism and infection intensities could be due to linkage disequilibrium of IL4 with other genes such as IL13 and IL5, which in humans are located just 12.5 kb and 132 kb upstream of IL4 and are also key TH2 cytokines." (PMID 21501512, 2011). "As previous studies have shown that sterile immunity in schistosomiasis is dependent on IgE levels, eosinophils and on the Th1/Th2 balance, our laboratory decided to test whether any allelic variants in the IL4, IL5 and IL13 genes would predispose individuals to high infection levels by Schistosoma." (PMID 19471606, 2008). "Previous studies have demonstrated that central IL-13 levels are elevated during restraint stress as well as following peripheral administration of bacterial lipopolysaccharides, a surrogate of infection." (PMID 40775068, 2026). "In severe infection, mRNAs of IL‐4, IL‐5, IL‐6, IL‐10 and IL‐13 highly expressed compared to the non‐infected control, but the interferon‐ (INF)‐γ expression remained unaltered." (PMID 41503693, 2026). "Overexpressed in keratinocytes of AD patients, IL-33 is rapidly released in response to injury or infection, triggering Th2 polarization by activating immune cells such as mast cells and group 2 innate lymphoid cells (ILC2s) to produce IL-4, IL-5, and IL-13." (PMID 41020006, 2025). "Compared to D614G and BA.2 infection, IL-13 secretion was significantly upregulated with Gamma, Delta, and BA.1 infections (p < 0.0001)." (PMID 40295859, 2025). "TSLP release in response to RV infection and stimulation with IL-4 was significantly increased in asthmatic BECs as compared with healthy BECs, and the same was observed after stimulation with IL-4 and IL-13 on top of infection with RV." (PMID 40370530, 2025). "This cluster peaked at 2 days post infection but showed a lower magnitude of expression across all post infection timepoints due to IL-13 pretreatment." (PMID 41427379, 2025). "In subtype C, we found that the changes in the biomarker profiles post infection compared to pre-infection were due to increases in TNFα, IL-10, IL-6, IL-13, IL-5, IFNγ, IL-12, IL-4, ITAC, IL-17α, and IL-23." (PMID 40862133, 2025). "In terms of modulating early immune responses, IFN-γ, IL-1α, and IL-12p70 are crucial for infection control, while IL-13 and IL-18, found at higher levels in P4, assist in tissue repair and maintaining an anti-inflammatory environment." (PMID 40046233, 2025). "We analyzed levels of cytokines at the site of infection including IFNγ, IL-10, IL-17, IL-4, and IL-13 by quantitative real-time PCR." (PMID 40655011, 2025). "IFNγ is essential for activation of macrophages for intracellular killing of S. aureus but is modulated by production of IL-13 and other cytokines to prevent excess inflammation during response to infection." (PMID 39966757, 2025). "Consistent with changes in DNA methylation levels, expressions of Il4, Il13, Cd200, and Il1rl1 were highest on the first day of infection and gradually decreased over time." (PMID 40170749, 2025). "We observed that nine biomarkers (fractalkine, IFNγ, IL-5, IL-6, IL-10, IL-12, IL-13, IL-21, and TNFα) had significantly increased levels post-infection with subtype C HIV-1 compared to the pre-infection levels." (PMID 40862133, 2025).
infection (continued). "This response is characterized by the production of cytokines such as IL-4, IL-5, IL-6, IL-10, and IL-13, which deactivate infected macrophages and allow parasite dissemination at infection sites and internal organs." (PMID 40391226, 2025). "In mice ILC2-derived IL-13 promotes a rapid immune response and enhances bacterial clearance following infection with S. pneumoniae." (PMID 40568578, 2025). "To investigate the infection efficiency and expression levels of IL-4, IL-10, and IL-13 in modified MSCs, we examined their fluorescence and secretion levels." (PMID 40038782, 2025). "Systemically, MCP-1 recruits monocytes and dendritic cells to infection sites, while IL-4/IL-13 drives B-cell class switching, and IL-10/TGF-β modulate inflammation to prevent tissue damage." (PMID 40668875, 2025). "At the same time, IL-13 expression was significantly increased compared to the NC after infection with KR5." (PMID 40426284, 2025). "In contrast, in subtype A infected individuals, only two biomarkers (IL13 and TNFα) had significantly increased levels post-infection." (PMID 40862133, 2025). "Mice deficient in Irf4 in CD11c+ cells secrete less IL-4, IL-5, and IL-13 both in the SI and colon after infection with the parasite Schistosoma mansoni, and a similar outcome is observed after infection with T. muris and Nippostrongylus brasiliensis." (PMID 41028655, 2025). "Whilst initial infection stimulates a mixed Th1/Th2 cytokine response, parasite egg production from 4-5 weeks post-infection promotes a dominant type 2 inflammatory response with high levels of IL-4, IL-5 and IL-13 (weeks 6–8)." (PMID 41296814, 2025). "The concentration of chemokines CxCL1/KC/GRO-α, CxCL2/MIP-2, CCL5/RANTES and cytokines TNF-α, IL-1β, IFN-γ, IL-5, IL-6, IL-9, IL-10, IL-13, IL-17, IL-23 circulating in blood were measured in experimental animals on day 15 post-infection." (PMID 40445994, 2025). "- Predominant granulocyte at infection site (~2.5 h).- Adhere to parasite via Fc–Fc interaction with IgG.- Contribute to a Th2 cytokine secretion (IL-4, IL-13)." (PMID 41479896, 2025). "p43 binds directly to IL-13 and blocks the activity of this cytokine, inhibiting IL-13 responses during infection." (PMID 40302223, 2025). "In murine models, eosinophil accumulation is driven by cytokines such as IL-13, which promotes recruitment to the infection site, and IL-4, which enhances IgE production." (PMID 41479896, 2025). "After 8 weeks of infection, lesions that were comparable in size to those of wild-type animals were found in IL-13 knockout mice." (PMID 39963187, 2025). "Infection with helminths induces polarized type 2 immunity characterized by elevated expression of cytokines, including IL-4, IL-5, IL-10, and IL-13." (PMID 38166140, 2024). "It is reported that IL-33 from type II alveolar epithelial cells aids to killing the infected larvae of S. venezuelensis in the lungs by inducing the proliferation of ILC2 and production of IL-5 and IL-13 during the primary infection." (PMID 39559705, 2024). "The goblet cell response that follows infection with H. diminuta was delayed in Pou2f3-/- mice, possibly as a consequence of reduced or delayed IL-4/IL-13 signaling downstream of tuft cell activation." (PMID 39083533, 2024). "In general, the Il-4 and Il-13 gene expression profiles of co-infected animals were more similar to Hb than Tg infected animals at day 5 post Tg infection." (PMID 38950025, 2024). "At days 4, 6, 8, and 10 PI, visually distinct patterns between infection parameters from baso IL-4/IL-13 (−) mice and baso IL-4/IL-13 (+) mice provided ample significant correlations and fold differences for network analyses." (PMID 38780542, 2024). "Mast cells, basophils, dendritic cells, neutrophils, monocytes, and macrophages have prominent roles whereby IL-4/IL-13 polarizing cytokines participate in resolving the infection in favor of the host." (PMID 38392907, 2024).